FMR1 (fragile X messenger ribonucleoprotein 1)
Diseases named in the same sentence as FMR1 in open-access papers (continued):
Sharing a sentence is not in itself a finding about the gene and the disease.
Kinetic tremor (1 paper, 2018). Tremor that occurs during any voluntary movement. "FXTAS classically presents with kinetic tremor and cerebellar gait ataxia in elderly male FMR1 premutation carriers, and also female premutation carriers with a milder form of FXTAS have been reported." (PMID 29316893, 2018).
Korsakoff’s syndrome (1 paper, 2021). "Genetic testing revealed a 77 CGG repeat in the FMR1 gene, and his initial diagnosis of Korsakoff’s syndrome was retracted." (PMID 33709078, 2021).
lymph node metastasis (1 paper, 2025). "Immunohistochemistry further indicated that high FMR1 expression was significantly associated with lymph node metastasis and advanced TNM stage (P < 0.05), but not with age, sex, differentiation, invasion depth, or tumor diameter." (PMID 41184982, 2025).
male infertility (1 paper, 2020). The inability of the male to effect fertilization of an ovum after a specified period of unprotected intercourse. "CFTR, mutations of which are associated with male infertility, might be coregulated by FXR1, HNRNPA1, MATR3, PABPC1, G3BP2, FMR1, and SRSF7." (PMID 32316190, 2020). "EGFR, the signalling dysfunction of which was associated with human male infertility, might be coregulated by FXR1, FXR2, and HNRNPA1 (all of these three bind EGFR from CLIP experiments), G3BP2, G3BP1, FMR1, and SRSF7." (PMID 32316190, 2020).
ovarian dysgenesis (1 paper, 2025). "Nevertheless, 39 patients (61.9%) had no candidate variants detected by WES or FMR1 testing, including P46, who has sister with the same manifestations (ovarian dysgenesis)." (PMID 41393291, 2025).
postpartum depression (1 paper, 2022). A type of clinical depression that occurs after childbirth. "In addition, the preconception women with FMR1 PM alleles were found to be at increased risk for FXPOI, postpartum depression and neuropsychiatric disorders." (PMID 35246105, 2022). "In addition, the preconception women with FMR1 PM alleles were found to be at increased risk for primary ovary insufficiency (RG1: P = 0.0265, RG2: P = 0.0389), postpartum depression (RG1: P = 0.0240, RG2: P = 0.0501) and neuropsychiatric disorders (RG1: P = 0.0389, RG2: P = 0.0432)." (PMID 35246105, 2022).
proteinopathy (1 paper, 2018). "Summary of FMR1 premutation carriers with pathologically-confirmed concomitant proteinopathy." (PMID 30158953, 2018).
Rubinstein-Taybi syndrome (1 paper, 2022). A rare malformation syndrome characterized by congenital anomalies (microcephaly, specific facial characteristics, broad thumbs and halluces and postnatal growth retardation), short stature, intellectual disability and behavioral characteristics. "Trichostatin A at 2 mg/kg, which is an effective dose to improve cognitive functions in a mouse model of Rubinstein-Taybi syndrome, failed to improve object location memory in Fmr1 KO mice." (PMID 34791268, 2022).
Sepsis (1 paper, 2025). Sepsis is defined as life-threatening organ dysfunction caused by a dysregulated host response to infection. "Building on this, our findings of significantly higher FMR1 expression in CD8+ T cells suggest its contribution to the necroptosis in sepsis, warranting further investigation of the underlying mechanisms." (PMID 40861493, 2025). "In sepsis, FMR1 expression has been associated with altered immune cell function and inflammatory responses; moreover, the absence of FMRP induces TNF-mediated apoptosis and necroptosis in infections and liver diseases." (PMID 40861493, 2025).
sleep disorder (1 paper, 2017). A change from the patient's baseline sleeping pattern, in the hours slept and/or an alteration/dysfunction in the stages of sleep. "Our data highlight the importance of the fragile X genes (Fmr1 and Fxr2) in sleep physiology and confirm the utility of these mouse models in enhancing our understanding of sleep disorders in FXS." (PMID 28919851, 2017).
spindle cell neoplasm (1 paper, 2025). A benign or malignant neoplasm characterized by the presence of neoplastic spindle cells. "FMR1-ALK-rearranged cutaneous myxoid spindle cell neoplasm: This entity shows myxoid stroma and whole spindle cell arrangement but lacks pigmentation and NTRK fusion." (PMID 41409361, 2025).
status epilepticus (1 paper, 2024). Status epilepticus is defined as a continuous seizure lasting more than 30 min, or two or more seizures without full recovery of consciousness between any of them. "In a previous study where we induced status epilepticus (continuous seizures) in Fmr1 KO mice on PD10, we found an increase in consecutive nose pokes." (PMID 39335388, 2024).
steatosis (1 paper, 2024). Increased lipid within the cytoplasm of cells. "Overall, there are varied adverse health events associated with multiple single-source diets in Fmr1-mutant mice: chows (Fmr1KO, seizures), soy/purified (Fmr1KO, increased weight gain), and casein/purified (steatosis)." (PMID 38257177, 2024).
substance dependence (1 paper, 2024). The psychological or physiological need to take a substance in order to experience its effects or to avoid the effects of its absence. "Gene set enrichment analysis further highlighted substance dependence and drug reinforcement as significantly enriched pathways in the Fmr1 KO ventral striatum." (PMID 39308631, 2024).
synovial sarcoma (1 paper, 2024). "On the other hand, the expression of RBM15 and FMR1 was significantly downregulated in synovial sarcoma tissue, suggesting they might have an important role in tumor suppression." (PMID 38549939, 2024).
synucleinopathies (1 paper, 2018). "Moreover, larger studies are needed in order to assess whether the FMR1 premutation and/or other epigenetic factors are related to predispose tauo- and synucleinopathies." (PMID 30158953, 2018).
testicular germ cell tumor (1 paper, 2022). A germ cell tumor arising from the testis. "The result of the prognostic value of FMR1 is in line with previous research where the expression levels of FMR1 were positively correlated with the overall survival of testicular germ cell tumors." (PMID 36189296, 2022).
Tetralogy of Fallot (1 paper, 2017). A congenital cardiac malformation comprising pulmonary stenosis, overriding aorta, ventricular septum defect, and right ventricular hypertrophy. "Mutations in NKX2-5 (5q35.1), GATA4 (8q23.1), ZFPM2 (8q23.1), GATA6 (18q11.2), GDF1 (19p13.11), JAG1 (20p12.2), and TBX1 (22q11.21) have been reported in sporadic cases with tetralogy of Fallot; however, interaction of these genes and FMR1 gene has never been reported." (PMID 28751920, 2017).
transient ischaemic attacks (1 paper, 2021). "As both donors also suffered from multiple vascular incidents in the brain, this suggests that apart from cellular dysfunction, problems in the brain vasculature can contribute to the FMR1-premutation phenotype where infarcts or transient ischaemic attacks can disrupt blood supply." (PMID 33709078, 2021).
urothelial carcinoma (1 paper, 2022). A malignant neoplasm derived from the transitional epithelium of the urinary tract (urinary bladder, ureter, urethra, or renal pelvis). "This study confirmed the prognostic value of FMR1 and HNRNPA2B1, and constructed a nomogram for individualized prediction of the response to atezolizumab in patients with urothelial carcinoma, which may aid in making treatment strategies." (PMID 36189296, 2022).
X-chromosome disorder (1 paper, 2025). "This X-chromosome disorder is predominantly caused by a CGG trinucleotide repeat expansion in the 5′-untranslated region (UTR) of the FMR1 gene, which causes the transcriptional silencing of the promoter and the loss of expression of fragile X messenger ribonucleoprotein (FMRP)." (PMID 40649914, 2025).
X-linked disease (1 paper, 2020). X-linked form of disease. "X-linked disease, caused by the expansion mutation of a CGG repeat sequence in the FMR1 gene, encoding for a protein essential for synaptic plasticity, neuronal morphology, and cognitive development." (PMID 32582026, 2020).
neurodevelopmental disorder (101 papers, 2011 to 2026). A behavioral and cognitive disorder with onset during the developmental period that involves impaired or aberrant development of intellectual, motor, or social functions. "Pathological mutations in the FMR1 protein disrupt its physiological functions, contributing to neurodevelopmental disorders." (PMID 40588021, 2025). "This supports using whole exome sequencing (WES) as an initial diagnostic tool for neurodevelopmental disorders (NDDs), surpassing targeted molecular studies like FMR1 triplet expansion or aCGH." (PMID 39941308, 2025). "Recently, diseases associated with intermediate FMR1 CGG repeat lengths have been extended by the fragile X–associated neurodevelopmental disorders (FXANDs) that usually include anxiety and depression." (PMID 36991279, 2023). "In this model, FMR1 is important in development, and loss of/reduced expression or malfunction of this protein is rather associated with neurodevelopmental disorders." (PMID 36991279, 2023). "FXS is a neurodevelopmental disorder caused by loss of function mutations in the X-linked FMR1 gene which encodes Fragile X Mental Retardation Protein (FMRP), an RNA binding protein." (PMID 35588990, 2022). "Fragile X syndrome (FXS) is a neurodevelopmental disorder caused by the full mutation as well as highly localized methylation of the fragile X mental retardation 1 (FMR1) gene on the long arm of the X chromosome." (PMID 35216055, 2022). "The author suggested that either a loss or a gain copy number of the FMR1 gene, which is tightly regulated, is essential for the normal development of neurocognitive structures and functions, and can lead to neurodevelopmental disorders." (PMID 35646065, 2022). "FXS is a neurodevelopmental disorder that affects intellectual, social, and physical development due to a mutation of the FMR1 gene, for which treatment options are still limited and alternative therapies are needed." (PMID 35629320, 2022). "Fragile X syndrome (FXS) is a neurodevelopmental disorder due to an X-linked mutation in the FMR1 gene." (PMID 34440392, 2021). "Fragile X syndrome (FXS) is an inherited neurodevelopmental disorder caused by a full-mutation expansion [>200 trinucleotide (CGG) repeats] in the promoter region of the fragile X mental retardation 1 (FMR1) gene." (PMID 34690787, 2021). "Large CGG repeat expansions (> 200 repeats) in the fragile X mental retardation 1 (FMR1) X-linked gene, labelled ‘full mutations’, cause the Fragile X syndrome (FXS), a neurodevelopmental disorder resulting from decreased FMR1 translation." (PMID 34116720, 2021). "We concentrated on the Fragile X syndrome gene Fmr1 because mutation of this gene was the major cause of this neurodevelopmental disorder, which was associated with aberrant neuronal migration." (PMID 30911036, 2019). "FXS is a common hereditary neurodevelopmental disorder associated with the X-linked gene FMR1 (fragile X mental retardation-1), which is highly expressed in neurons." (PMID 28545252, 2017). "This neurodevelopmental disorder is caused by the loss of the Fragile X mental retardation protein (FMRP) encoded by the Fragile X mental retardation 1 (FMR1) gene." (PMID 27047540, 2016). "Replication of independent findings of enrichment of SFARI ASD risk genes and FMR1 protein networks, as well as layer 2/3 neuronal dysregulation in the pathogenesis of neurodevelopmental disorders also indicated that our approach detected meaningful biological perturbations." (PMID 38826276, 2024).
neurodevelopmental disorder (continued). "This serious neurodevelopmental disorder is caused by missing or insufficient production of fragile X mental retardation protein (FMRP) in neurons in the brain resulting from expanded CGG repeats on intron 1 of the FMR1 gene on the X chromosome." (PMID 35034602, 2022). "This work advances our understanding of how FMR1 integrates multiple layers of RNA regulation through its domain architecture, with important implications for neurodevelopmental disorders." (PMID 40588021, 2025). "Recent studies have established FMR1 as an m6A reader protein, revealing a direct connection between mRNA modifications and neurodevelopmental disorders including autism spectrum disorder (ASD)." (PMID 40588021, 2025). "Encouragingly, we replicated past findings of neurodevelopmental disorders in our own gene expression data, including enrichment of known pathogenic ASD risk genes, FMR1 protein target genes, and dysregulation of layer 2/3 excitatory neurons 7,9,27,30." (PMID 38826276, 2024). "Given that FX is a neurodevelopmental disorder, we used a relevant human model to assess the effects of AsA treatment on FMR1 in cerebral organoids." (PMID 39684429, 2024). "Among the genes associated with neurodevelopmental disorders, FMR1 is a well-characterized gene that encodes the RNA-binding protein FMRP." (PMID 38804677, 2024). "To validate the utility of our genetic labeling approach to study neurodevelopmental disorders, we used this approach to characterize spine development in fmr1 mutants." (PMID 35875841, 2022). "On the other hand, FXS is a neurodevelopmental disorder that results from a full mutation (FM) allele (CGG expansions of ≥200 repeats) leading to heterochromatization and transcriptional silencing of the FMR1 gene." (PMID 36110216, 2022). "FXS is an X-linked, neurodevelopmental disorder caused by a CGG trinucleotide repeat expansion in the 5′ untranslated region (UTR) of the Fragile X Mental Retardation gene, FMR1." (PMID 34679478, 2021). "Together these results extend the degree of synaptic GABAergic alterations in FXS, now to the mPFC of Fmr1-KO mice, a behaviourally relevant brain region in neurodevelopmental disorder pathology." (PMID 32528248, 2020). "Given the multicomponent aspects of attentional processing, disrupted in neurodevelopmental disorders, we assessed attentional processing in Fmr1-KO mice using the 5CSRTT." (PMID 24312033, 2013). "In a sample of 378 children with normal intelligence and no chronic disease and/or neurodevelopmental disorder, 4 children were identified as having expanded FMR1 alleles." (PMID 35719251, 2022). "Our results, providing for the first time a characterization of the behavioral phenotype of the Fmr1-KO mouse model at an advanced age, support the relevance of aging as a sensitive period for the effects of genetic insults, also in the context of neurodevelopmental disorders." (PMID 36385949, 2022). "An environmental model of neurodevelopmental disorders in which mice were exposed to maternal immune activation (MIA) during embryogenesis has been compared with mouse models that were genetically deficient for Cntnap2, Fmr1, or Shank3." (PMID 34065644, 2021). "Although studies vary in the level of phenotypic detail provided, several authors reporting on yields of CMA, ES, and FMR1 CGG repeat analysis in patients with neurodevelopmental disorders suggest that specific characteristics and additional diagnoses are associated with increased diagnostic yields." (PMID 33681094, 2021). "Interestingly, they also report hypoactivity in the active phase in three other mouse models of neurodevelopmental disorders: Cntnap2−/−, Pcdh10+/−, and Fmr1 KO mice." (PMID 33396736, 2020). "FXS is a neurodevelopmental disorder caused by a CGG repeat expansion in the X-linked fragile X mental retardation 1 (FMR1) gene, which results in the transcriptional silencing of FMR1, and subsequent reduction of its protein product, fragile X retardation protein (FMRP)." (PMID 31200759, 2019).
neurodevelopmental disorder (continued). "Hence, stress could be a valuable tool to enhance the face validity of the Fmr1-KO mouse model for neurodevelopmental disorders, an issue that has been recently questioned, together with its predictive validity." (PMID 36385949, 2022). "This complex neurodevelopmental disorder is caused by an alteration in the CGG trinucleotide expansion in fragile X mental retardation gene 1 (FMR1) leading to gene silencing and the subsequent loss of its product: fragile X mental retardation protein 1 (FMRP)." (PMID 34966298, 2021). "Finally, it is worth mentioning that mGluRI activation is found to be abnormal in other neurodevelopmental disorders, in which FMR1 and FMRP are not mutated in any way, and are normally expressed in the CNS." (PMID 30899214, 2019). "Altogether, the present findings showing accumulation of iron in distinct Fmr1 KO mouse tissues are fundamental and promote further research to evaluate role of biometals in FXS and other neurodevelopmental disorders." (PMID 34089433, 2021). "This neurodevelopmental disorder is the result of a trinucleotide expansion in the FMR1 gene that results in the reduction or absence of the fragile X messenger ribonucleoprotein (FMRP), a critical factor in brain development and synaptic plasticity." (PMID 35624962, 2022). "This study supports a preservation of striatal DAT availability following FMR1 deletion in rats and confirms that in vivo SPECT imaging paralleled by behavioral observation represents a useful tool to non-invasively investigate variations in neurotransmitter activity in neurodevelopmental disorders." (PMID 36581671, 2022).